SLC1A5 (solute carrier family 1 member 5)
Diseases named in the same sentence as SLC1A5 in open-access papers (continued):
Sharing a sentence is not in itself a finding about the gene and the disease.
cancer (continued). "Based on the indication from the GSEA results that SLC1A5 is closely related to cancer immunity, we investigated the correlation between the expression of SLC1A5 and immune cell infiltration across cancers." (PMID 37566748, 2023). "Dysregulated c-Myc in CAF upregulates GLS and SLC1A5, enhances both glycolysis and glutaminolysis, and increases the secretion of metabolic intermediates such as glutamate to feed neighboring cancer cells." (PMID 36768660, 2023). "The uptake of these glutamine into the cancer cells are mediated by alanine-serine-cysteine-transporter-2 (ASCT2 or SLC1A5) and it was observed that there was increased expression of these transported in LC patients." (PMID 36851259, 2023). "GSEA was performed based on the differentially expressed genes between the low-SLC1A5 subgroup and the high-SLC1A5 subgroup to evaluate the cancer characteristics related to SLC1A5 in each cancer type." (PMID 37566748, 2023). "Taken together, our results suggest that SLC1A5 affects the progression, treatment and prognosis of cancer patients by regulating immune cells." (PMID 37566748, 2023). "It has been confirmed that circ_0000069, circ_0000808 and circ_0025033 all positively regulate SLC1A5 and glutamine metabolism through ceRNA mechanisms to promote cancer progression." (PMID 37365670, 2023). "Because SLC1A5 is a double-edged sword in cancer progression, it is important to unravel its function in different cancers." (PMID 36902506, 2023). "In conclusion, we conducted a pancancer analysis of SLC1A5, demonstrated its role as a prognostic biomarker in cancer patients and explored its potential biological functions." (PMID 37566748, 2023). "Using triple negative breast cancer cells as a model, a recent large-scale, unbiased proteomic screen carried out to identify proteins that interact with CAIX in hypoxic cancer cells revealed that CAIX associates with the glutamine transporter, SLC1A5." (PMID 38099193, 2023). "The analysis of genomic alterations of SLC1A5 showed that alterations of SLC1A5 are common across cancers; they are most UCS at a rate of 5%, and amplification is the most common alteration type." (PMID 37566748, 2023). "Another amino acid transporter, ASCT2/SLC1A5, has been shown to be overexpressed in various carcinomas, making it an ideal target for cancer-specific drug delivery." (PMID 36770817, 2023). "The GSEA results showed that SLC1A5 is involved in immune activation processes and closely related to the infiltration levels of different immune cells in different cancer types." (PMID 37566748, 2023). "SLC1A5, a membranous importer, is required for the uptake of neutral amino acids (e.g., Gln) and contributes to metabolic reprogramming of cancer cells." (PMID 36654781, 2023). "In conclusion, we conducted a pancancer analysis of SLC1A5, demonstrated its role as a prognostic biomarker in cancer patients, explored its potential biological functions, and found that it can effectively predict patient response to immunotherapy." (PMID 37566748, 2023). "The results indicated that across cancers, SLC1A5 was mainly expressed in immune cells (especially monocytes/macrophages) and malignant cells." (PMID 37566748, 2023). "Alternatively, the corresponding transporters and enzymes have been found to be highly expressed in these cancer patient samples, such as SLC1A5, GLS, and GLUD1." (PMID 36077501, 2022). "As a glutamine transporter, SLC1A5 is capable of providing glutamine for proliferative cancer cells." (PMID 35419359, 2022). "Nevertheless, the link between the transporter SLC1A5 and oncogenic MYC expression and adverse prognosis in a variety of cancers prompted the development of the SLC1A5 inhibitor as a target of pharmacological blockage." (PMID 36499623, 2022).
cancer (continued). "The PPARβ/δ agonist GW501516 induced the expression of Glut1 (glucose transporter 1) and SLC1A5 (solute carrier family 1 member 5), which favors glucose and glutamine influx, thereby enhancing the proliferation of different cancer cell lines in vitro." (PMID 35954274, 2022). "Targeting of glutamine uptake via the transporter protein ASCT2/SLC1A5 (solute carrier family 1 member 5) is considered to be an effective strategy for the treatment of malignant tumors." (PMID 35418865, 2022). "Extracellular Asn is important to quantify, as it can be transported into cancer cells by SLC1A5 and aid in tumor growth." (PMID 36090030, 2022). "Research shows that cancer cells have an increased amount of glutamine transporters, including ASCT2 (SLC1A5)." (PMID 35628385, 2022). "The c-Myc-regulated amino acid transporter ASCT2 (SLC1A5) regulates the glutamine uptake in cancer cells." (PMID 35216362, 2022). "On the other hand, SLC1A5 serves as a glutamine transporter that is responsible for meeting the enormous demands of glutamine for cancer cell proliferation." (PMID 35419359, 2022). "The proposed theme is that when glutamine is taken up by cancer cells via SLC1A5, it is converted into glutamate by GLS." (PMID 36499623, 2022). "ATF4 has been verified as a critical regulator of nutrient metabolism in many kinds of cancers, and its target genes include SLC1A5 and ASNS." (PMID 35864117, 2022). "SLC1A5 is upregulated in many forms of cancer that are characterized by rapid progression, anti-cancer drug resistance and poor survival outcome." (PMID 35008407, 2022). "In a variety of cancers, targeted inhibition of SLC1A5 has been shown to reduce glutamine metabolism and thereby inhibiting cancer progression." (PMID 36192755, 2022). "Among these transporters, SLC1A5, also known as ASCT2 (the alanine, serine, cysteine, and glutamate transporter), has been well-studied in various cancers." (PMID 36499136, 2022). "The Oncomine pan-cancer analysis revealed that SLC1A5 overexpression widely occurred in multiple cancers." (PMID 35419359, 2022). "It is important to note that SLC1A5-mediated glutamine metabolism played an important role in regulating ferroptosis in cancer cells." (PMID 35041678, 2022). "SLC1A5 is highly expressed in many cancers, including CRC, and plays an important role in supplying glutamine for energy production, autophagy, redox homeostasis, and activation of mTOR signaling, thereby promoting tumor growth." (PMID 35418865, 2022). "We then asked why PHGDH inhibition cannot be compensated for with exogenous serine, one possible explanation is the relatively low-baseline mRNA expression of the serine transporter SLC1A5 in OS cells, as shown in data from the Cancer Cell Line Encyclopedia." (PMID 35186770, 2022). "SLC1A5 levels are increased in tissues that need high levels of glutamine for metabolism, as well as in cancer cells, including cancer from tissues that normally lack SLC1A5." (PMID 35755805, 2022). "Due to the central core status in the ferroptosis process and critical function in glutamine metabolism (a double-edged sword in cancer), SLC1A5 was selected as the original intention of our study." (PMID 35419359, 2022). "SLC1A5 is highly expressed in many cancers, and the pharmacological blockade of SLC1A5 by V9302 for cancer treatment is now under preclinical trials." (PMID 36566214, 2022). "MiR-137 was negatively correlated with SLC1A5, suggesting that SLC1A5 is a key target of miR-137, inhibiting the growth of cancer cells." (PMID 35305616, 2022). "SLC1A5 is overexpressed in many primary human neoplasms which indicates its role in maintaining the necessary level of energy metabolism in cancer cells." (PMID 35628385, 2022). "Since SLC1A5 is responsible for intracellular glutamine supply, it is pivotal for maintaining the energetic demands from vigorous cancer cells." (PMID 35419359, 2022).
cancer (continued). "Based on the existing evidence, SLC1A5 is an important target in the process of tumor cell progression, and new evidence shows that SLC1A5 inhibitors can provide considerable therapeutic effect for cancer treatment." (PMID 35501667, 2022). "The exogenous expression of miR-137 and miR-122 markedly inhibited SLC1A5 expression in a dose-dependent manner and was identified as altering glutamine metabolism in cancer." (PMID 36013278, 2022). "We performed a systematic analysis of the correlation of SLC1A5 expression with the prognosis of cancer patients attested to in several databases, including Oncomine, PrognoScan, Gene Expression Profiling Interactive Analysis (GEPIA), and Kaplan-Meier plotter." (PMID 34367941, 2021). "Inhibition of SLC1A5 impedes glutamine uptake, leading to disturbance of mTORC1 signaling and activation of autophagy and cancer cell growth." (PMID 34708125, 2021). "We used gene expression data from TCGA to assess SLC1A5-related OS in 33 types of cancers with the Kaplan-Meier method." (PMID 34367941, 2021). "In PrognoScan, we explored the relation between SLC1A5 expression and the prognosis of each type of cancer." (PMID 34367941, 2021). "In cancer cells, glutamine is mainly transported to the mitochondria by SLC1A5 (solute carrier family 1 member 5) to participate in TCA." (PMID 34604067, 2021). "To determine SLC1A5 expression in cancer in more detail, we examined expression in pan-cancers based on the TCGA database." (PMID 34367941, 2021). "Another important aspect of this study is that SLC1A5 expression correlated with the extents of multiple immune cell infiltration in cancers, especially LGG and HCC." (PMID 34367941, 2021). "First, the correlation of SLC1A5 expression and immunity in cancer was analyzed on the basis of publicly available expression datasets." (PMID 34367941, 2021). "A recent study identified a small-molecule drug candidate, IMD-0354, that targets the glutamine transporter SLC1A5 to inhibit the uptake of glutamine by cancer cells, blocking an important energy source for cancer cells and thus, slowing their growth." (PMID 34604067, 2021). "High SLC1A5 expression has been recently reported in different types of cancer, and identified as a prognostic marker of adverse outcome." (PMID 34282517, 2021). "In both of these cancers, most of the 48 marker genes showed a positive correlation with SLC1A5 expression, with the highest correlation being found between SLC1A5 and a T helper cell 9 (Th9) marker PU.1 (SPI1), which is an oncogene." (PMID 34367941, 2021). "In recent years, several reports have shown the tumor growth‐promoting role of SLC1A5/ASCT2 in several cancers." (PMID 34003553, 2021). "While fourteen proteins are known to transport extracellular glutamine into cells, SLC1A5/ASCT2 is thought to be the major transporter, and its expression is upregulated in various cancers." (PMID 35127483, 2021). "Next, we investigated the prognostic value of SLC1A5 for pan-cancer recorded in different databases." (PMID 34367941, 2021). "In this study, we found that SLC1A5 was overexpressed in most cancer tissues compared with normal ones using independent datasets in Oncomine." (PMID 34367941, 2021). "The overexpression of SLC1A5 (also known ASCT2), a sodium-dependent transporter for neutral amino acids with high affinity for Gln, is highly expressed in several cancer types, especially those with MYC overexpression." (PMID 34445444, 2021). "Blocking the expression of SLC1A5 through V-9302 reduces cancer cell growth and proliferation and increases cell death and oxidative stress, thereby leading to antitumor efficacy both in vitro and in vivo." (PMID 34367941, 2021). "SLC1A5 is commonly highly expressed in cancer and can inhibit the biological behaviors of cancer cells by reducing glutamine uptake." (PMID 34738502, 2021).
cancer (continued). "Usually, GLN is transported into cancer cells mostly by alanine-serine-cysteine-transporter-2 (also called SLC1A5) followed by SLC6A14 and SLC38A5." (PMID 34503536, 2021). "According to the Cancer Cell Line Encyclopedia project and other studies, SLC1A5 is overexpressed in many solid cancers, such as colon, gastric, lung, and prostate cancers." (PMID 34503536, 2021). "Cancer cells absorb GLN through SLC1A5 and efflux it through SLC7A5 in exchange for leucine and other essential amino acids (EAAs)." (PMID 34503536, 2021). "Gln firstly enters cells via Gln transporters such as solute carrier family A1 member 5 (SLC1A5), which is essential for cancer cell growth." (PMID 35223460, 2021). "Recently, SLC1A5 has received great attention for its membrane protein characteristics and potential role in cancers, which has made it a druggable therapeutic target." (PMID 34367941, 2021). "The amino acid transporter SLC1A5 has emerging importance as a prognostic marker and potential therapeutic target in various types of cancer." (PMID 34282517, 2021). "Other amino acids play important roles in biosynthesis and intracellular redox homeostasis in cancer cells, such as cysteine, isoleucine, threonine and valine, and they have been found to significantly decrease in SLC1A5-knockout cells." (PMID 33429909, 2021). "SLC1A5, a key transporter in charge of moving glutamine across the cytomembrane and mitochondrial membrane, is involved in several cancers." (PMID 34367941, 2021). "Here are just a few examples: SNAT1 (SLC38A1), SNAT2 (SLC38A2), and ASCT2 (SLC1A5) are the major Gln transporters in cancer cells." (PMID 33477430, 2021). "ASCT2/SLC1A5 and ATB0+ are among the Gln-specific transporters identified to be overexpressed in numerous cancer cells (Bröer and Bröer, 2017)." (PMID 34345235, 2021). "A 18F labeled alanine trifluoroborate (18F-Ala-BF3) is a selective SLC1A5 marker for cancer imaging in the gastric cancer xenograft models." (PMID 33401748, 2021). "SLC1A5 overexpression induced by HIF-2α-mediated hypoxia in cancer cells plays a key role in cancer metabolic reprogramming." (PMID 34604067, 2021). "V-9302, a competitive small molecule antagonist of SLC1A5, was shown to attenuate cancer cell growth and induce cancer cell apoptosis due to increased oxidative stress." (PMID 33374949, 2020). "The transporters that stand out as potential targets to reduce cancer cell growth are ASCT2 (SLC1A5), LAT1 (SLC7A5), CAT1 (SLC7A1), GC1 (SLC25A22), and SNAT2 (SLC38A2)." (PMID 32859034, 2020). "The uptake of extracellular serine and glycine is required for migration, and motility of cancer cells can be effectively impaired by using inhibitors of the serine/glycine transporters SLC1A4/SLC1A5 and GlyT1, which are involved in this process." (PMID 33243973, 2020). "Among AATs upregulated in cancer, the alanine-serine-cysteine transporters 2 (ASCT2, encoded by SLC1A5) has been spotlighted as a therapeutic target because it is the primary glutamine transporter and many cancers show glutamine addiction." (PMID 32824193, 2020). "The fifth member of the SLC1 family, ASCT2 (SLC1A5), attracted the attention of the membrane transport scientific community in the last years for its link with the metabolic rewiring occurring in cancer cells." (PMID 32733894, 2020). "GLS is not the only marker associated with glutamine metabolism; the glutamine transporter ASCT2 (SLC1A5) is actively investigated as a possible therapeutic target to block cancer cell growth and development." (PMID 32974128, 2020). "Recently, a potent inhibitor of SLC1A5, V-9302, has been reported to be effective in several cancer cell lines and in vivo tumor models." (PMID 32943735, 2020). "Cancers with MYC amplification exhibit elevated expression of amino acid transporters SLC1A5 and SLC38A5, as well as glutamine-metabolizing enzyme, GLS." (PMID 31627186, 2019).
cancer (continued). "The uptake of circulating glutamine into proliferating and cancer cells is mediated by the alanine-serine-cysteine-transporter-2 (ASCT2 or SLC1A5)." (PMID 30634602, 2019). "In many cancer cells, amino acid transporters are upregulated to enable rapid cell growth and are therefore potential drug targets e.g. as SLC1A5, SLC6A15, SLC7A5, and SLC7A11." (PMID 29868606, 2018). "Other than glutamine depletion, inhibition of glutamine transporter was also studied for anti-cancer drug design, up-regulated glutamine transporter targets SLC1A5/38A2 are recently reported in different cancer types." (PMID 28750681, 2017). "In the hope of inhibiting SLC1A5 in cancer therapy, and because of the similar use of glutamine in cancer cells and the immune cells, understanding the role of SLC1A5 in the immune system is crucial." (PMID 28553292, 2017). "The high expression levels of SLC1A5 has been reported to be closely related to poor prognosis in many cancers." (PMID 29100325, 2017). "Despite this, studies on the role of SLC1A5 in immune cells, which are themselves crucial to combating cancer, have only recently begun." (PMID 28553292, 2017). "Relevant to cancer, the neutral amino acid transporters ASCT2/SLC1A5 and LAT1/SLC7A5 are known to have higher expression in certain tumors, and can mediate glutamine uptake in cell lines derived from these tumors." (PMID 28826492, 2017). "Relative to other glutamine transporters, the ASC family transporter 2 (ASCT2, also called SLC1A5) is profoundly elevated in a wide spectrum of human cancers to coordinate metabolic reprogramming and malignant transformation." (PMID 28692032, 2017). "The higher levels of SLC1A5 in various types of cancer cells are considered to be essential for cell proliferation and survival via the mTOR/p-70S6K1 signalling pathway." (PMID 29100325, 2017). "Consistent with previous findings in other cancers types, high SLC1A5 expression was identified as an independent adverse prognostic factor for OS in ccRCC." (PMID 26599282, 2015). "To date, SLC1A5 has been regarded as an indispensable “switch” of glutamine metabolism and thus to be a critical regulator for cancer development." (PMID 26599282, 2015). "SLC1A5 is directly regulated by the nutrient-sensing Myc extended network member MondoA in many human cancer cells." (PMID 26197457, 2015). "c-Myc coordinately with MondoA/Mlx is essential for regulation of glutaminolysis in cancer cells and is also necessary for the induction of SLC1A5 in KSHV-infected endothelial cells." (PMID 26197457, 2015). "In summary, this detailed analysis not only underscores the significance of SMGs, particularly PHGDH and SLC1A5, in cancer biology but also lays the groundwork for unravelling the complex molecular mechanisms through which serine influences the tumour microenvironment and immune architecture." (PMID 40660426, 2025). "Here, we integrated in silico and in vitro approaches-including gene expression analysis, receptor inhibition, and AI-based protein modeling-to show that poly(L-glutamate) (PLE)-coated LbL-NPs bind with high avidity to SLC1A5, a glutamine transporter overexpressed in cancer." (PMID 41431241, 2025). "ASCT2(SLC1A5) is the main glutamine transporter in many cancer cell lines." (PMID 40944200, 2025). "The inhibition of SLC1A5 decreases glutamine uptake and inhibits cancer growth." (PMID 40362545, 2025). "SLC1A5 has long been a focus of investigation in cancer pathophysiology, where it is noted to be upregulated in numerous cancer cell lines by metabolic transcriptional regulators such as c-MYC and the kinase mTOR, which governs cancer cell proliferation, growth, and survival." (PMID 38792190, 2024). "In this article we identify ASCT2 (SLC1A5) as an important serine transporter in cancer cells." (PMID 39068660, 2024). "SLC1A5 then increases cancer cell growth, invasion, and metastasis, while decreasing apoptosis." (PMID 38705513, 2024).